PLEKHA7 (pleckstrin homology domain containing A7)
Description:
Required for zonula adherens biogenesis and maintenance. Acts via its interaction with CAMSAP3, which anchors microtubules at their minus-ends to zonula adherens, leading to the recruitment of KIFC3 kinesin to the junctional site. Mediates docking of ADAM10 to zonula adherens through a PDZD11-dependent interaction with the ADAM10-binding protein TSPAN33.
Synonyms: DKFZp686M22243
Tractability: PROTAC: ubiquitination databases record sites on it; its protein half-life has been measured.
Gene: Protein-coding gene on chromosome 11 (16,777,297 to 17,014,420, reverse strand). Ensembl gene ENSG00000166689.
Subcellular location: Cell junction, adherens junction; Cytoplasm; Cytoplasm, cytoskeleton, microtubule organizing center, centrosome
Subcellular location (Human Protein Atlas): Cell Junctions; Nucleoplasm; Cytosol
Gene Ontology:
Molecular function: delta-catenin binding; protein binding
Biological process: epithelial cell-cell adhesion; pore complex assembly; zonula adherens maintenance; cell-cell adhesion mediated by cadherin; cell-cell adhesion
Cellular component: cell junction; centrosome; cytoplasm; cytosol; extracellular exosome; nucleoplasm; pore complex; zonula adherens; adherens junction; cell-cell junction
Genetic constraint (gnomAD): Loss-of-function variants: 98 observed, 159.64 expected, observed/expected ratio (o/e) 0.61, 90% interval 0.52 to 0.73. The upper end of that interval is the gene's LOEUF score, 0.73, which puts it in group 2 of 6, group 1 being the genes least tolerant of losing a copy. Missense variants: 1,579 observed, 1,650.7 expected, observed/expected ratio (o/e) 0.96, 90% interval 0.92 to 1. Synonymous variants: 635 observed, 646.69 expected, observed/expected ratio (o/e) 0.98, 90% interval 0.92 to 1.05.
Homologues: Orthologues: macaque PLEKHA7 (99% identical), chimpanzee PLEKHA7 (94% identical), dog PLEKHA7 (94% identical), mouse Plekha7 (90% identical), pig PLEKHA7 (89% identical), rabbit PLEKHA7 (88% identical), guinea pig PLEKHA7 (86% identical), rat Plekha7 (84% identical), tropical clawed frog plekha7 (61% identical), zebrafish plekha7b (61% identical). Paralogues in human: PLEKHA5 (32% identical), PLEKHA6 (24% identical), PLEKHA4 (20% identical).
Diseases named in the same sentence as PLEKHA7 in open-access papers:
PLEKHA7 is named in the same sentence as 38 diseases in open-access papers, as found by Europe PMC text mining. Sharing a sentence is not in itself a finding about the gene and the disease. The quoted sentences say what the papers report.
glaucoma (7 papers, 2019 to 2024). Increased pressure in the eyeball due to obstruction of the outflow of aqueous humor. "Genome-wide association studies show that single nucleotide polymorphism in the PLEKHA7 gene are associated with human hypertension and high systolic pressure, and with primary angle closure glaucoma." (PMID 32371390, 2020). "Pleckstrin homology domain–containing A7 (PLEKHA7) is a cytoplasmic protein at adherens junctions that has been implicated in hypertension, glaucoma, and responses to Staphylococcus aureus α-toxin." (PMID 32371390, 2020). "Importantly, PLEKHA7 (Pleckstrin Homology Domain Containing A7) has been associated with Primary Angle Closure Glaucoma." (PMID 34834521, 2021). "So far, several GWAS studies of glaucoma have identified over 100 risk loci, including mutations in the CYP1B1, OPTN, and PLEKHA7 genes." (PMID 34834521, 2021). "We aimed to investigate the association between the identified susceptible genetic markers PLEKHA7 rs11024102, ABCC5 rs17217796, and KALRN rs1392912 in the progression of primary angle-closure glaucoma (PACG) in Malay patients." (PMID 34804680, 2021). "PLEKHA7 and COL11A1 were genotyped for single-nucleotide polymorphisms (SNPs) to investigate the possible association of these two genes with primary angle-closure glaucoma (PACG) and disease severity." (PMID 30809385, 2019). "PLEKHA7, ABCC5, and KALRN have been identified as susceptible genetic markers related to glaucoma." (PMID 34804680, 2021). "PLEKHA7 and ABCC5 gene expressions were found in structures relevant to glaucoma such as the iris, ciliary body, choroid, and aqueous humour outflow." (PMID 34804680, 2021). "Furthermore, DNA methylation studies identified DMRs in glaucoma-related genes, such as PLEKHA7 and PITX2, between primary open-angle glaucoma (POAG) patients and normal Schlemm’s canal cells, reinforcing the link between methylation and glaucoma pathology." (PMID 39678047, 2024).
Hypertension (7 papers, 2014 to 2023). The presence of chronic increased pressure in the systemic arterial system. "Genome-wide association studies in human cohorts implicate PLEKHA7 in blood pressure and hypertension." (PMID 35714771, 2022). "PLEKHA7 is implicated by genetic studies in hypertension and the regulation of calcium handling." (PMID 35714771, 2022). "Among them, pleckstrin homology domain containing family A member 7 (Plekha7) is a plausible candidate gene for essential hypertension identified by GWAS." (PMID 36009402, 2022). "However, generalization of previously implicated hypertension (GRM7, SLC4A7, ADAMTS9) and SBP-associated loci (PLEKHA7) from cross-sectional analyses with much larger sample sizes, provide strong evidence that these statistical models are robust." (PMID 26866891, 2016). "The 1 SNP (rs11606492) that yielded significant results from both PDT and PPATu (but not PPAT) is within the gene PLEKHA7 that has been implicated to be associated with hypertension in previous studies." (PMID 25519332, 2014).
colon cancer (5 papers, 2020 to 2025). "When PLEKHA7 was restored in colon cancer cell lines, the RNAi machinery was also restored to apical AJ and PLEKHA7-expressing xenografts showed a reduced tumor burden." (PMID 33525380, 2021). "Recent work in colon cancer patient samples demonstrated concomitant dysfunction of PLEKHA7 and the RNAi machinery at the apical AJs during colon cancer progression." (PMID 33525380, 2021). "In agreement with our previous findings in breast and kidney tissues, we found that PLEKHA7 is extensively mis-localized in colon tumors from all stages." (PMID 32272708, 2020). "We show that the restoration of PLEKHA7 expression at adherens junctions of aggressively tumorigenic colon cancer cells restores the junctional localization of RNAi components and suppresses cancer cell growth in vitro and in vivo." (PMID 32272708, 2020). "More specifically, apical and/or junctional localization of PLEKHA7 appears to be either fragmented or the protein downregulated in colon tumors." (PMID 32272708, 2020). "The depletion of PLEKHA7 expression in colon cancer cells has been shown to disrupt ZA organization, suggesting that PLEKHA7 may maintain AJ integrity in epithelial cells." (PMID 36823376, 2023). "Moreover, we have reported that the junctional localization of PLEKHA7 and RNAi components is broadly disrupted in colon tumors." (PMID 36497003, 2022). "Importantly, the apical junctional localization of RNAi proteins is disrupted or lost in human colon tumors and in poorly differentiated colon cancer cell lines, correlating with the dysregulation of the adherens junction component PLEKHA7." (PMID 32272708, 2020). "Together, these data demonstrate that a key difference between normal and tumor colon tissues of all stages appears to be the loss of apical junctional or of any cell-cell junction localization of the PLEKHA7-RNAi complex in colon tumors, compared to normal colon epithelial tissues." (PMID 32272708, 2020). "In addition to the three colon cancer cell lines that PLEKHA7 is still expressed in but its junctional localization disrupted, we identified one, namely HCT116, in which PLEKHA7 is downregulated." (PMID 32272708, 2020). "However, we have not assessed the status of PLEKHA7 in colon tumors." (PMID 32272708, 2020).
breast carcinoma (3 papers, 2015 to 2023). "We used viral transduction to re-express PLEKHA7 in inflammatory breast cancer cells and examined their aggressiveness in 2D and 3D cultures and in vivo." (PMID 33525380, 2021). "The data indicate that PLEKHA7 is frequently deregulated and acts to suppress inflammatory breast cancer." (PMID 33525380, 2021). "Here, we used immunohistochemistry of inflammatory breast cancer patient samples and analysis of cell lines to determine the expression of PLEKHA7, an apical adherens junction protein." (PMID 33525380, 2021). "To study PLEKHA7 expression in human breast carcinomas, we examined cohorts of non lobular, predominantly ductal carcinoma, and lobular breast carcinomas of different stage, grade and hormonal status." (PMID 26270346, 2015).
depression (2 papers, 2020 to 2024). "It is possible that alterations in cell-cell communication effected by changes in transcription or expression of PLEKHA7 could be markers of risk for depression more generally, and for perinatal depression only as a special case of this broader association." (PMID 32066670, 2020). "Overall, this study highlights the significant roles of TRUB1, PLEKHA7, and FABP6 in the development of depression associated with COVID-19." (PMID 39588145, 2024). "In summary, this research highlights the roles of TRUB1, PLEKHA7, and FABP6 as hub genes, the underlying pathways and TF–miRNA networks, and the potential impact of these genes on immune cell activity in the development of depression and COVID-19." (PMID 39588145, 2024). "Our findings revealed that TRUB1 and PLEKHA7 expression was decreased, whereas FABP6 expression was increased in both the depression group and the COVID-19 patient group compared with the control group." (PMID 39588145, 2024). "In this study, the genes TRUB1, PLEKHA7, and FABP6 emerged as central hubs potentially contributing to the pathogenesis of both depression and COVID-19." (PMID 39588145, 2024).
lung adenocarcinoma (2 papers, 2023 to 2024). A carcinoma that arises from the lung and is characterized by the presence of malignant glandular epithelial cells. "In conclusion, this case report described a novel ALK double-fusion involving PLEKHA7-ALK and INPP5D-ALK in lung adenocarcinoma." (PMID 38379102, 2024). "This is the first case presenting a rare concomitant ALK double-fusion, namely PLEKHA7-ALK and INPP5D-ALK, in a patient with lung adenocarcinoma, who exhibited favorable sensitivity to alectinib." (PMID 38379102, 2024). "Here, we reported a case with concomitant ALK rare double-fusion, namely PLEKHA7-ALK and INPP5D-ALK in a patient diagnosed with lung adenocarcinoma who showed favorable response to alectinib following chemotherapy failure." (PMID 38379102, 2024).
ovarian carcinoma (2 papers, 2018 to 2021). A malignant neoplasm originating from the surface ovarian epithelium. "In certain ovarian epithelial cancer lines, E-cadherin has been shown to promote EGFR signaling, and this is suppressed by expression of PLEKHA7." (PMID 33525380, 2021). "Increased junctional and decreased cytoplasmic β-catenin localization upon PLEKHA7 expression was also observed in an ovarian cancer model but alterations to β-catenin-nuclear activity were not tested in that study." (PMID 33525380, 2021).
colorectal tumors (1 paper, 2020). "Importantly, our analysis combined with the analysis of publicly available data from TCGA, shows that E-cadherin is still widely expressed in colorectal tumors, whereas PLEKHA7 is overall downregulated." (PMID 32272708, 2020).
ductal carcinomas (1 paper, 2015). "PLEKHA7 immunolabeling was strongly decreased in G3 ductal carcinomas and undetectable in lobular carcinomas." (PMID 26270346, 2015). "Our results, showing that PLEKHA7 accumulates at junctions of epithelial cells forming gland or tubular structure, indicate that PLEKHA7 expression can be used to more precisely grade tubular formation in ductal carcinoma." (PMID 26270346, 2015). "PLEKHA7 was detected at epithelial junctions of normal mammary ducts and lobules, and of tubular and micropapillary structures within G1 and G2 ductal carcinomas." (PMID 26270346, 2015). "This indicated that the decreased or undetectable expression of PLEKHA7 in high grade ductal carcinomas and lobular carcinomas is not due to decreased mRNA levels." (PMID 26270346, 2015).
gastric cancer (1 paper, 2023). A primary or metastatic malignant neoplasm involving the stomach. "Increased hTERT dramatically decreased PLEKHA7 expression and promoted invasion and metastasis in gastric cancer cells." (PMID 36823376, 2023). "We observed that the expression of PLEKHA7 in gastric cancer was significantly negatively associated with the TNM stage and lymphatic metastasis and that decreased PLEKHA7 expression dramatically increased invasion and metastasis in gastric cancer cells." (PMID 36823376, 2023). "Here, we report that hTERT promotes gastric cancer invasion and metastasis by recruiting p50 to synergistically inhibit PLEKHA7 expression." (PMID 36823376, 2023). "To further confirm whether PLEKHA7 plays a critical role in negatively regulating migration/invasion ability of gastric cancer cell, we applied genetic methods to deplete endogenous PLEKHA7 in cells." (PMID 36823376, 2023). "To understand the regulatory mechanism of PELKHA7 expression, we treated gastric cancer cells (MKN74) and immortalized gastric epithelial cells (GES-1) with cycloheximide D and MG-132, respectively, and detected PLEKHA7 expression at different times." (PMID 36823376, 2023).
gastric tumour (1 paper, 2023). "After identifying the most significant difference in PLEKHA7 expression between gastric tumour tissues and adjacent tissues, we analysed the effect of PLEKHA7 on the prognosis of GC patients." (PMID 36823376, 2023). "Compared with the respective paired normal tissues, PLEKHA7 expression was the most significantly different in the gastric tumour tissues." (PMID 36823376, 2023). "To confirm that reduced PLEKHA7 expression contributes to gastric tumour progression, we performed a range of biochemical and pathological statistical analyses, and the results showed that patients with lower PLEKHA7 expression exhibited lower overall survival." (PMID 36823376, 2023). "Moreover, the gradual decrease in PLEKHA7 expression was regulated by the hTERT/p50 complex, which is dominated by hTERT action, during gastric tumour metastasis." (PMID 36823376, 2023).
Hip dysplasia (1 paper, 2021). The presence of developmental dysplasia of the hip. "MED13 (Chr 9) and PLEKHA7 (Chr 21) emerged as novel positional candidate genes associated with hip dysplasia." (PMID 34474664, 2021).
inflammatory breast carcinoma (1 paper, 2021). An advanced, invasive breast adenocarcinoma characterized by the presence of distinct changes in the overlying skin. "We determined that PLEKHA7 was deregulated in inflammatory breast cancer, demonstrating improper localization or lost expression in most patient samples and very low expression in cell lines." (PMID 33525380, 2021). "While deregulation of PLEKHA7 is not specific to inflammatory breast cancer, IBCs consistently express and require E-cadherin and p120 for their growth and aggressive behavior." (PMID 33525380, 2021).
invasive ductal carcinoma (1 paper, 2021). "We and others have found that PLEKHA7 is primarily cytoplasmic in invasive lobular carcinoma, presumably due to E-cadherin loss, while in invasive ductal carcinoma, PLEKHA7 expression is predominantly lost." (PMID 33525380, 2021). "This is highly consistent with previous reports that PLEKHA7 is lost or mislocalized in invasive ductal carcinoma." (PMID 33525380, 2021).
kidney tumors (1 paper, 2020). "We also introduced data from breast and kidney tumors showing extensive mis-localization or downregulation of PLEKHA7." (PMID 32272708, 2020).
lobular carcinoma (1 paper, 2015). "To this purpose, here we studied the expression and localization of PLEKHA7 in human breast invasive ductal and lobular carcinomas by immunohistochemistry, immunofluorescence, and quantitative RT-PCR." (PMID 26270346, 2015). "Again supporting the immunohistochemistry results, PLEKHA7 labeling was undetectable in frozen sections of lobular carcinoma." (PMID 26270346, 2015). "PLEKHA7 expression was assessed in invasive ductal and lobular carcinomas of the breast by immunohistochemistry, immunofluorescence and quantitative RT-PCR." (PMID 26270346, 2015). "PLEKHA7 mRNA was detected in both ductal and lobular carcinomas, with no observed correlation between mRNA levels and tumor type or grade." (PMID 26270346, 2015). "In contrast, we did not observe cytoplasmic staining for PLEKHA7 above background, in either normal breast or ductal or lobular carcinoma, using both frozen and formalin fixed paraffin embedded sections." (PMID 26270346, 2015). "We could not detect PLEKHA7 labeling in lobular carcinomas despite the occurrence of PLEKHA7 mRNA." (PMID 26270346, 2015).
lung carcinoma (1 paper, 2024). "The PLEKHA7-ALK fusion was first reported as an acquired drug resistance in a patient with lung cancer who had failed to adequately respond to osimertinib." (PMID 38379102, 2024).
metanephric adenoma (1 paper, 2024). A benign, well-circumscribed renal cortical neoplasm affecting females more often than males. "Additionally, ALK::STRN and ALK::PLEKHA7 gene fusions have been described in tumors mimicking metanephric adenoma, corroborating the notion that gene fusion partners might impact morphology and even clinical outcomes." (PMID 37999735, 2024).
primary closed-angle glaucoma (1 paper, 2019). "Mutations in collagen type XI alpha 1 chain (COL11A1) and pleckstrin homology domain containing A7 (PLEKHA7) genes were designated as crucially important risk factors for the development of primary closed-angle glaucoma." (PMID 31949441, 2019).
prostate carcinoma (1 paper, 2020). A carcinoma that arises from epithelial cells of the prostate gland. "Some of the genes associated with these 16 sites included PLEKHA7, AP1M2, ATP9A, and ARVCF known to be downregulated in breast and prostate cancer (data not shown), as well as other cancers." (PMID 32503656, 2020).
renal cell carcinoma (1 paper, 2024). "In addition, the PLEKHA7-ALK fusion was also reported in renal cell carcinoma." (PMID 38379102, 2024).
Sepsis (1 paper, 2023). Sepsis is defined as life-threatening organ dysfunction caused by a dysregulated host response to infection. "Disruption of skin barrier integrity by reducing levels of either junctional proteins (e.g., E-cadherin, ZO-1, ZO-3, PLEKHA7) or the receptors for Hla may underlie other consequences and pathologies such as Ca2+ influx or sepsis." (PMID 37651426, 2023).